CD4 (CD4 molecule)
Diseases named in the same sentence as CD4 in open-access papers (continued):
Sharing a sentence is not in itself a finding about the gene and the disease.
influenza (continued). "We recently demonstrated that the expansion of peripheral blood influenza-specific CD4+IL-21+ICOS1+ T helper (TH) cells, three weeks after vaccination, associated with and predicted the rise of protective neutralizing antibodies to avian H5N1." (PMID 27336786, 2016). "Overall, these results strongly suggest that the frequency hierarchy of CD4+ T cells specific to seasonal influenza vaccination and viral exposure is at least partially determined at the stage of repertoire generation and thymic selection." (PMID 27571776, 2016). "The large contribution of lower-affinity CD4+ T cells was also found in the NP311–325-specific T-cell population responding during influenza x31 infection and NP311/CFA immunization." (PMID 27976744, 2016). "Memory CD8+ T cells generated in influenza infection down-regulate gp130 and CD4+ T cells in persistently-infected salivary glands expressed less gp130 expression than splenic CD4+ T cells during acute infection." (PMID 27926930, 2016). "This diversity of influenza-specific CD4 T cells in humans has raised intriguing issues and challenges relevant for predicting vaccine responses and protection from influenza infection." (PMID 26834750, 2016). "We previously showed that antigen-specific blood CD4+IL-21+ICOS+ TH cells expand three weeks after influenza vaccination." (PMID 27336786, 2016). "Analysis of memory status via CD45RA expression revealed that most influenza-specific CD4+ T cells were of the memory phenotype as expected given that all epitopes had been included in the vaccine since at least 2012." (PMID 27571776, 2016). "Assays were carried out with whole (inactivated) H1N1 virus using mixed PBMC (containing detectable influenza-specific IL-2+CD4+ T cells) and pooled human AB serum containing anti-H1N1 Abs to standardize the level of influenza-specific IgG in cultures." (PMID 27233958, 2016). "Young and aged mice received young polyclonal CD45.1+ CD4+ T cells one day prior to influenza infection." (PMID 27109638, 2016). "Our data thus far indicate that aged influenza-specific CD4+ T cells differentiate normally to a pre-TFH cell phenotype, but less progress to a mature GC phenotype compared to young mice." (PMID 27109638, 2016). "As proof of principle, we analyse CD4+ T-cell responses to the seasonal influenza vaccine, establishing a frequency hierarchy and examining differences in memory and activation status, lineage commitment and cytokine expression." (PMID 27571776, 2016). "Because of the importance of neutralizing antibodies in protection from influenza, we have explored the role of viral protein specificity in provision of CD4 T cell help for antibody responses to vaccines and infection." (PMID 26834750, 2016). "We have found that the relatively small pool of HA-specific memory CD4 cells that can be recruited into the response to novel strains of influenza will vary among individuals, likely reflecting their exposure history with seasonal influenza." (PMID 26834750, 2016). "Obesity has also been identified as an independent risk factor for increased susceptibility to influenza virus infection; this susceptibility results from diminished CD4+ and CD8+ T-cell responses and lower influenza vaccine antibody levels." (PMID 27821093, 2016). "Sustained signaling from CD28 is critical for Tfh survival as evidence from apoptosis of Tfh cells during influenza viral or Citrobacter rodentium infection into a mice strain that after initial priming selectively lose CD28 expression on CD4 T cells." (PMID 27933060, 2016). "Results presented herein provide evidence that endogenous, aged antigen-specific CD4+ T cells exhibit a defect in their ability to fully differentiate to a GC TFH cell phenotype in response to influenza infection." (PMID 27109638, 2016).
influenza (continued). "So it seems that while the CD4 T cell response needed to generate an antibody response in our aging model is adequate, the ability to generate lung-homing Th1 effectors during influenza infection is less preserved with aging." (PMID 27177221, 2016). "Various studies have begun to elucidate the factors that drive CD4 CTL differentiation during influenza infection in vivo." (PMID 27014272, 2016). "CD40 is also involved in the self-help feedback loop of influenza-specific CD4+ T cells, in which previously primed CD4+ T cells license DCs to better prime the next generation of CD4+ T cells." (PMID 26910342, 2016). "GrB and perforin double staining has been shown by this technique and our lab is pursuing this method to further understand the expression patterns of GrB and perforin and how that relates to degranulation in CD4 CTL during influenza infection." (PMID 27014272, 2016). "This subset has been associated with activating mainly CD4+ T cells, although recently it was shown that these cells too can stimulate CD8+ T cells in the context of influenza infection." (PMID 27030971, 2016). "Many questions arise from this model that seeks to quantify and predict the impact of memory CD4 on influenza immunity." (PMID 26834750, 2016). "For example, in mouse models, they are able to confer protection independently of B cells and CD8 T cells, and in humans, protection was correlated with preexisting influenza-specific CD4 T cells." (PMID 27446083, 2016). "Since these influenza-specific CD4 T cells are primed during vaccination, they are poised to traffic to the lungs at the first sign of infection, prior to other unprimed T cell populations." (PMID 27177221, 2016). "We chose to adoptively transfer polyclonal CD4 T cells in this system to provide a broad repertoire of influenza-specific naïve precursors to provide B cell help." (PMID 25569154, 2015). "Here, we describe a novel influenza vaccine platform based on the generation of antigen-specific CD4 and CD8 T cells capable of reducing viral titers after lethal IAV challenge." (PMID 26161083, 2015). "Stimulation of peripheral blood mononuclear cells (PBMC) from a subset of acute patients with peptide T-cell epitopes showed significantly lower frequencies of influenza specific CD8+ compared with CD4+ IFN-γ T-cells in acute patients." (PMID 26606759, 2015). "A randomised controlled study of trivalent inactivated influenza vaccine conducted in HIV-infected adults with CD4+ T cell counts >200 μg/ml in South Africa reported 75% (95% CI 9.2-95.6) efficacy in adults." (PMID 25623944, 2015). "For instance, a dose of 2.5 μg WIV adjuvanted with cationic lipid/DNA complex (CLDC) was able to induce influenza-specific CD4+ and CD8+ T cell responses in mice, whereas alum adjuvanted WIV only induced high-antibody responses." (PMID 26029218, 2015). "In summary, these data indicate that CD4+ T cells are involved in the immune response to influenza infection in pigs and that a considerable proportion of responding cells is multifunctional in terms of IFN-γ, TNF-α and IL-2 production." (PMID 25971313, 2015). "In the DLNs, CD69 expression was differentially upregulated in CD8 cells after CpG + Inact or influenza immunization while only PR8 infection resulted in increases in CD4 cells." (PMID 26161083, 2015). "To extend these findings, we conducted a detailed ex vivo phenotypic analysis of Ag-specific CD4+ T cells expanded by influenza vaccination." (PMID 26553072, 2015). "Formulations with AS03B (especially the 0.003 μg/dose) also generated more influenza-specific CD4+ and CD8+ T cells than the unadjuvanted or AS03A-adjuvanted vaccines, although these cells were primarily single positive for IFNγ." (PMID 25972874, 2015). "First, we confirmed that the host-derived OT-II CD4 T cells remained naïve (CD44lo) throughout the influenza infection." (PMID 25569154, 2015).
influenza (continued). "The main function of CD4+ T cells during influenza infections is to aid the development of cytotoxic T cells and antibodies." (PMID 26257735, 2015). "In this study, we demonstrate that direct TGF-β signaling to CD4 T cells is important for the formation of influenza-specific Tfh cells, GC reactions, and development of isotype-switched, flu-specific antibody responses." (PMID 25569154, 2015). "CD4+ T-cells play a key role in anti-influenza immunity both in direct killing through intrinsic effector mechanisms and by stimulating cells of the adaptive or innate immune system." (PMID 26343192, 2015). "The role of CD4+ T-cells in mediating protection against influenza is becoming increasingly evident." (PMID 26343192, 2015). "IL-27 has also been shown to cooperate with IL-2 from CD4+ helper T cells to induce IL-10 through a Blimp-1 dependent mechanism during influenza infection." (PMID 25651926, 2015). "Optimal activation of CD4 cells are likely to require a longer incubation period with influenza and syncytin-1." (PMID 25831059, 2015). "A small number of CD4+ T cells were responsible for the release of IFN-γ in response to influenza and there was a trend to reduced release with syncytin-1." (PMID 25831059, 2015). "In contrast to CD8+ T-cells, the influenza-specific Th1 CD4+ T-helper cell response to vaccination increases following vaccination, albeit the durability of this response is less clear." (PMID 26343192, 2015). "In our study, we evaluated CMI based on Th1-specific activation marker expression after in vitro re-stimulation of influenza-specific CD4+ and CD8+ T-cells." (PMID 24628789, 2014). "The reduced impact of age on influenza-specific CD4 T cells was consistent with a reduced effect of age on the overall CD4 compared with the CD8 T cell repertoire in specific pathogen free mice." (PMID 24999367, 2014). "The in vitro immune response of memory CD4+ T cells against seasonal and pandemic (-like) influenza vaccines showed major differences compared to that of the CD8+ subset." (PMID 25072749, 2014). "In summary, seasonal and pandemic (-like) influenza whole virus vaccines loaded on monocyte-derived DC effectively stimulated heterosubtypic virus-specific CD4+ as well as CD8+ memory T cells in vitro." (PMID 25072749, 2014). "Specifically, the current data show that the repertoire of influenza NP-specific CD4 T cells, assessed by Vβ usage, was only mildly perturbed in aged mice." (PMID 24999367, 2014). "The induction of T and B cells is an important component of the immune response, and CD4+ effector and memory T cells have various protective roles in the innate response to influenza infection." (PMID 24628789, 2014). "Higher influenza-specific CD4+ T cell responses and NP-specific CD8+ T cell responses were associated with increased protective efficacy." (PMID 24523886, 2014). "Each of the immune markers was detected in influenza-specific CD4+ T cells both before and after vaccination in the three groups." (PMID 25078387, 2014). "While intranasal immunization stimulated the production of protective antibodies, vaccination via this route also promoted the generation of influenza-specific Th17 CD4+ T cells." (PMID 24465206, 2014). "We next tested the contribution of CD25 in the generation of CD4 CTL in vivo in response to acute influenza infection." (PMID 24586481, 2014). "In comparison to CD8+ T cells, the role of CD4+ T cells in influenza is less well understood, partly due to their heterogeneity and the lack of epitope-specific systems." (PMID 24971078, 2014). "The relative proportions of the different influenza-specific CD4+ T-cell phenotypes appeared similar for the three groups." (PMID 25078387, 2014). "Given the role of IL-2 and IL-2Rα in the generation of cytolytic effectors in vitro, we next wanted to determine the contribution of IL-2Rα (CD25) in the generation of CD4 CTL in vivo in response to acute influenza infection." (PMID 24586481, 2014).
influenza (continued). "This is illustrated for influenza infection, in which a high number of virus-specific CD4+ T cells in patients infected with pandemic influenza A virus from 2009, correlated with more severe illness." (PMID 24795718, 2014). "In the same donor cohort (n = 10), IFN-γ ELISpot reactivity of CD4+ T cells to whole virus and split virus vaccine preparations was very similar for most influenza strains." (PMID 25072749, 2014). "We compared Tbet expression in human influenza-specific CD4 T cells with Tbet levels in tetanus-specific cell populations, which contain uncommitted Thpp cells." (PMID 24788814, 2014). "DC (DC) or influenza infected DC (DCF) were co-cultured with either CD4 or CD8 T cells in an ELISPOT assay." (PMID 25475068, 2014). "Understanding the impact of ageing on CD4 T cells is important for vaccine design because it has recently been shown that pre-existing influenza-specific CD4 T cells correlate with disease protection against influenza challenge in humans." (PMID 24999367, 2014). "Such trials should include a careful monitoring of the full repertoire of influenza-specific CD4+ and CD8+ T cells, for which the current data are certainly helpful." (PMID 25072749, 2014). "To confirm that vaccine-primed IL-17A-secreting CD4+ T cells are indeed prototypical Th17 cells, we first assessed the expression of RORγT and T-bet in flu-specific CD4+ T cells in the lungs of mice at 5 days following influenza challenge." (PMID 24465206, 2014). "Since the adaptive immune response is paramount in the host defense against pathogens, we focused our studies on the subset of CD8+ and CD4+ T cells instrumental in controlling and clearing intracellular pathogens such as influenza." (PMID 25358535, 2014). "After infection there is expansion of influenza-specific T cells in the medLN, peaking at 6 days post infection, accompanied by substantial migration of antigen-specific effector CD4+ T cells into the lung." (PMID 25347065, 2014). "H5N1 split-virion A/Vietnam/1194/2004 influenza vaccine with AS03(A) resulted in increased production of polyfunctional H5N1-specific CD4+ T cells in volunteers aged 18–60 years." (PMID 26344621, 2014). "In contrast, correlations have been identified after boosting with A(H5N1) prime/boost influenza vaccination regimens, and by examining particular CD4+ T-cell phenotypes." (PMID 25078387, 2014). "A limited number of influenza viral peptides generate a focused CD4+ and CD8+ response, which is termed immune-dominance." (PMID 23951151, 2013). "It has also been shown that memory CD4+ T cells account decisively for a faster control of influenza infection on repeated exposure to the virus." (PMID 23967238, 2013). "Peptides spanning the proteome of temporally distinct influenza viruses were distributed into pools enriched for cross-reactivity to different influenza strains, and used to stimulate antigen-specific CD4 T cells representing recent or long-term memory." (PMID 23526940, 2013). "The human CD4 T cell memory response to influenza is normally skewed strongly to the Th1 pattern of cytokine expression, including mainly cells secreting IFNγ, TNFα and IL-2 but not IL-4." (PMID 23526940, 2013). "We first evaluated the cytokine expression patterns of antigen-specific CD4 T cell responses to influenza and tetanus in a cohort of healthy adults by ICS and 15-color flow cytometry." (PMID 23526940, 2013). "This indicates that the presence of MPL does not appear, in this setting, to be essential to achieve maximal enhancement of CD4 T cell responses to influenza antigens." (PMID 23890405, 2013). "In a mouse model for Influenza vaccinations the specific alterations of CD4+CD25+Foxp3+ regulatory T-cells (Tregs) in the immune modulation induced by orally supplied oligosaccharides containing scGOS/lcFOS/pAOS was assessed." (PMID 24073243, 2013).
influenza (continued). "Both pre-existing CD4 T cells specific for influenza virus and pre-existing anti-influenza NAb appeared to impact the magnitude of the CD4 T cell boost following TIV." (PMID 24155927, 2013). "Allelic variants of HLA class II molecules, through their role in antigen presentation to CD4+ T helper cells, most probably influence the adequacy of the immune response following influenza vaccination." (PMID 23951151, 2013). "The contribution of these CD4+ T cell mediated anti-viral activities in directly controlling influenza infection following vaccination with the gH1-Qβ vaccine require further studies for investigation." (PMID 24204639, 2013). "We have previously shown that the pTfh CD4 T cell subset resides almost exclusively in the memory CD4 T cell pool and that IL-21 production by pTfh is critical for influenza Ab response." (PMID 24236161, 2013). "Subjects with day 0 influenza-specific NAb titers had decreased CD4 T cell responses to H1, H3 and NP+M viral proteins at multiple time points after vaccination." (PMID 24155927, 2013). "Intriguingly, influenza-specific memory CD4+ T cells have also been reported to synergize with naïve B cells and CD8+ T cells to provide protection against influenza viral infection." (PMID 23516357, 2013). "Consistent with this, changes within the CD4+ naïve and memory subsets have been shown to impair long-term CD4+ T cell responses to influenza and hepatitis B vaccination." (PMID 26056568, 2013). "We found a stronger response in healthy individuals compared with pre-treatment levels of patients regarding influenza antigen-induced CD4+ and CD4+CD108+ T cell responses (166 ± 247 versus 39 ± 85 and 9.7 ± 14 versus 3.6 ± 5.1, respectively)." (PMID 24312575, 2013). "Dendritic cells (DC) transport viral antigens into the lymph nodes, where naïve T cells are converted into influenza antigen-reactive CD8+ cytotoxic T lymphocytes (CTL) or CD4+ T helper (Th) cells." (PMID 26056568, 2013). "CD4+CD108+ activated T helper cells showed a stronger response towards influenza antigen post-treatment (from 3.6 ± 5.1 to 9.7 ± 10)." (PMID 24312575, 2013). "T cell responses also correlate with disease protection against influenza; increased frequency of CD4+ T cells in particular correlate with lower virus shedding and less severe illness following infection with H3N2 or H1N1 viruses in seronegative humans." (PMID 24204639, 2013). "However, we found variability in reactivity to HA CD4+ T cell epitopes among donors, which could be correlated to factors such as age, previous exposure history to similar flu viral strains, genetics i.e. MHC class II allele promiscuity, and the binding affinity between MHC and its epitope." (PMID 23641949, 2013). "Most people have natural pre-existing immunity against influenza, comprizing both humoral and cellular immunity (CD4+ and CD8+ T cells), which can be beneficial to vaccination with influenza-virosomes." (PMID 23437055, 2013). "We therefore analyzed the CD4 T cell responses unique to recent and long-circulating strains of influenza to determine the impact of time on the quality (i.e. cytokine patterns) of memory T cells." (PMID 23526940, 2013). "In order to investigate the capacity of IFN-DC to re-activate autologous antigen specific T cells, IFN-DC were pulsed with influenza protein HA prior to co-culture with either autologous CFSE-labeled CD4+ T or CD8+ T cells." (PMID 23472200, 2013). "From the perspective of T cell immunity, future studies should examine its immunogenicity to CD4+ T cells, since CD4+ T cells to influenza core proteins correlated with disease limitations." (PMID 23527138, 2013). "Only the CW 1064 nm laser also significantly increased influenza-specific CD4+IL-5+ T-cell subpopulations (P<0.003)." (PMID 24349390, 2013).